ATF7IP (activating transcription factor 7 interacting protein)
Description:
Recruiter that couples transcriptional factors to general transcription apparatus and thereby modulates transcription regulation and chromatin formation. Can both act as an activator or a repressor depending on the context. Required for HUSH-mediated heterochromatin formation and gene silencing. Mediates MBD1-dependent transcriptional repression, probably by recruiting complexes containing SETDB1. Stabilizes SETDB1, is required to stimulate histone methyltransferase activity of SETDB1 and facilitates the conversion of dimethylated to trimethylated H3 'Lys-9' (H3K9me3). The complex formed with MBD1 and SETDB1 represses transcription and couples DNA methylation and histone H3 'Lys-9' trimethylation (H3K9me3). Facilitates telomerase TERT and TERC gene expression by SP1 in cancer cells.
Synonyms: ATF-IP; MCAF; MCAF1; FLJ10688; p621; ATF7IP1; AM
Tractability: PROTAC: UniProt records ubiquitination sites on it; ubiquitination databases record sites on it; its protein half-life has been measured.
Gene: Protein-coding gene on chromosome 12 (14,365,627 to 14,502,931, forward strand). Ensembl gene ENSG00000171681.
Subcellular location: Nucleus
Subcellular location (Human Protein Atlas): Nuclear bodies; Nucleoplasm
Pathways (Reactome):
Gene expression (Transcription): Regulation of endogenous retroelements by KRAB-ZFP proteins; Regulation of endogenous retroelements by the Human Silencing Hub (HUSH) complex
Chromatin organization: PKMTs methylate histone lysines
Gene Ontology:
Molecular function: protein binding; transcription coregulator activity; ATP hydrolysis activity; transcription corepressor activity
Biological process: DNA methylation-dependent constitutive heterochromatin formation; negative regulation of DNA-templated transcription; positive regulation of DNA-templated transcription; regulation of DNA-templated transcription
Cellular component: nuclear body; nucleoplasm; nucleus; transcription regulator complex
Genetic constraint (gnomAD): Loss-of-function variants: 18 observed, 90.76 expected, observed/expected ratio (o/e) 0.2, 90% interval 0.14 to 0.29. The upper end of that interval is the gene's LOEUF score, 0.29, which puts it in group 1 of 6, group 1 being the genes least tolerant of losing a copy. Missense variants: 1,227 observed, 1,473 expected, observed/expected ratio (o/e) 0.83, 90% interval 0.79 to 0.87. Synonymous variants: 507 observed, 526.98 expected, observed/expected ratio (o/e) 0.96, 90% interval 0.89 to 1.03.
Homologues: Orthologues: chimpanzee ATF7IP (99% identical), macaque ATF7IP (97% identical), dog ATF7IP (87% identical), pig ATF7IP (85% identical), rabbit ATF7IP (85% identical), guinea pig ATF7IP (82% identical), rat Atf7ip (76% identical), mouse Atf7ip (75% identical), tropical clawed frog atf7ip (48% identical), zebrafish atf7ip (22% identical), Drosophila melanogaster wde (18% identical). Paralogues in human: ATF7IP2 (14% identical).
Diseases named in the same sentence as ATF7IP in open-access papers:
ATF7IP is named in the same sentence as 36 diseases in open-access papers, as found by Europe PMC text mining. Sharing a sentence is not in itself a finding about the gene and the disease. The quoted sentences say what the papers report.
breast carcinoma (3 papers, 2013 to 2020). "The SP1 transcription factor is linked to breast cancer and Huntington's disease, acting together with ATF7IP to maintain telomerase activity via inducing the expression of TERT and TERC." (PMID 32157780, 2020). "We analyze in depth two regulatory variants—breast cancer risk SNP rs11055880 and leukemia risk-associated SNP rs12142375—and demonstrate their endogenous regulatory activities on expression of ATF7IP and PDE4B genes, respectively, using a CRISPR-Cas9 approach." (PMID 29061142, 2017). "Therefore, the association of the rs11055880-containing locus with breast cancer susceptibility may be related to modulation of the expression levels of ATF7IP." (PMID 29061142, 2017).
glioblastoma (2 papers, 2019 to 2021). The most malignant astrocytic tumor (WHO grade IV). "A prognostic model of glioblastoma was constructed based on SUMOylation regulator-related molecules (ATF7IP, CCNB1IP1, and LBH)." (PMID 33898460, 2021). "Finally, a prognostic model of glioblastoma was constructed based on SUMOylation regulator-related molecules (ATF7IP, CCNB1IP1, and LBH)." (PMID 33898460, 2021).
melanoma (2 papers, 2013 to 2017). A malignant, usually aggressive tumor composed of atypical, neoplastic melanocytes. "ATF7IP is a transcriptional cofactor that has been shown to be critical for heterochromatin formation by interacting with the histone methyltransferase SETDB1, an oncogene product promoting tumorigenesis in melanoma, lung cancer, and liver cancer." (PMID 29061142, 2017).
acute lymphoblastic leukemia (1 paper, 2024). Leukemia with an acute onset, characterized by the presence of lymphoblasts in the bone marrow and the peripheral blood. "study, where in ATF7IP::JAK2 mediated acute lymphoblastic leukemia (ALL), CHZ-868 is potent against the ruxolitinib resistant variants such as Y931C and L983F." (PMID 39091915, 2024).
acute myocardial infarction (1 paper, 2024). Necrosis of the myocardium, as a result of interruption of the blood supply to the area. "Knockdown of ATF7IP in this context was shown to improve acute myocardial infarction outcomes." (PMID 39734414, 2024).
adenoma (1 paper, 2022). A neoplasm arising from the epithelium. "Since these four tumors have the same SNV profile, we can assume that they harbor the genes that must be altered to make possible the transition from a silent to a clinically eloquent adenoma; the gene encoding ATF7IP (c.1589A > G [rs3213764], p.K529R) characterizes this clade." (PMID 35563252, 2022).
asthma (1 paper, 2020). "A similar situation was found in a novel lncRNA MSTRG.18506.1 which interacts with three asthma-related genes, i.e., SPDYE6, ATF7IP, VPS37A." (PMID 32948203, 2020). "Concretely, four genes (ATF7IP, SLC43A3, AKAP7, HMGN1) were found to be correlated to pathogenesis or treatment of asthma in immune." (PMID 32948203, 2020). "Notably, LINC02145 exhibited to be correlated to six asthma-related genes, including ZFN19, G2E3, ATF7IP, PEA15, SPDYE6, VWA5A." (PMID 32948203, 2020).
autoimmune disease (1 paper, 2014). A disorder resulting from loss of function or tissue destruction of an organ or multiple organs, arising from humoral or cellular immune responses of the individual to their own tissue constituents. "Notably, ATF7IP’s repressive partners MBD1 and SETDB1 have very different knockout phenotypes, namely mild spatial learning defects and autoimmune disease in adult mice lacking Mbd1, and early embryonic lethality at 3.5 to 5.5 days post conception for the Setdb1 deletion." (PMID 25028596, 2014).
colorectal cancer (1 paper, 2022). A primary or metastatic malignant neoplasm that affects the colon or rectum. "The variants described in ATF7IP and MSH3 are related to prostate and colorectal cancer, respectively." (PMID 35563252, 2022).
cryptorchidism (1 paper, 2021). The failure of one or both testes of a male fetus to descend from the abdomen into the scrotum during the late part of pregnancy. "Additionally, diseases that are associated with ATF7IP mostly involve a testis-related phenotype, and include testicular germ cell tumors, cryptorchidism and male infertility." (PMID 34795250, 2021).
endometrial cancer (1 paper, 2016). Primary or metastatic malignant neoplasm involving the endometrium (mucous membrane that lines the endometrial cavity). "Therefore, our study suggested ATF7IP as a new susceptibility locus in endometrial cancer." (PMID 26716509, 2016).
gastric cancer (1 paper, 2020). A primary or metastatic malignant neoplasm involving the stomach. "ATF7IP/MCAF1 is an epigenetic factor involved in heterochromatin formation and gene regulation, which is frequently overexpressed in various kinds of tumors including gastric cancers." (PMID 32012497, 2020). "Gastric cancer tissue and adjacent noncancerous regions showed high and low expression of ATF7IP/MCAF1, respectively." (PMID 32012497, 2020). "Gastric cancer tissue and adjacent noncancer regions showed high and low expression of ATF7IP/MCAF1, respectively, suggesting a correlation between the expression levels of this protein and H&E morphology." (PMID 32012497, 2020). "Based on the expression levels of ATF7IP/MCAF1, we then classified H&E images using wndchrm to low and high expression of this protein (CA 0.95‐1.00, which shows high accuracy, regardless of image numbers), suggesting that gastric cancer tissues as tested can be clearly divided to these two classes." (PMID 32012497, 2020).
lung adenocarcinoma (1 paper, 2023). A carcinoma that arises from the lung and is characterized by the presence of malignant glandular epithelial cells. "ATF7IP is inactivated in 5% of lung adenocarcinomas among non-smokers." (PMID 37686494, 2023).
male infertility (1 paper, 2021). The inability of the male to effect fertilization of an ovum after a specified period of unprotected intercourse. "These indications prompt for further investigation regarding the involvement of ATF7IP in male infertility and testicular cancer via regulation of imprinted and non-imprinted genes that are important for spermatogenesis." (PMID 34795250, 2021).
Prader-Willi syndrome (1 paper, 2021). "However, H3K9me3 levels throughout the Prader-Willi syndrome (PWS) locus encompassing SNRPN, were similar between WT and ATF7IP-KO or SETDB1-KO." (PMID 34795250, 2021).
testicular cancer (1 paper, 2021). A primary or metastatic malignant neoplasm that affects the testis. "Herein, more than 46% of samples that are associated with testicular cancer exhibited elevated copy numbers of a region on chromosome 12 containing ATF7IP." (PMID 34795250, 2021).
viral infections (1 paper, 2018). "During viral infections in humans, SP110 has been shown to interact with the Remodelling and Spacing Factor 1 (RSF1) and Activating Transcription Factor 7 Interacting Protein (ATF7IP), suggesting it is involved in chromatin remodelling." (PMID 30082726, 2018).
tumor (10 papers, 2018 to 2025). "CRISPR/Cas9-mediated KO of Setdb1 or its interacting partner Atf7ip (activating transcription factor 7-interacting protein) in multiple murine tumor models increased antigen expression and resulted in retardation of tumor growth in immunocompetent mice." (PMID 39519018, 2024). "Furthermore, the disruption of either SETDB1 or ATF7IP in tumor cells restores tumor antigen expression and augments tumor immunogenicity." (PMID 38057834, 2023). "Of particular interest was the top-ranking candidate in the ID4-eGFPBright dataset, activating transcription factor 7 interacting protein (ATF7IP), a transcriptional co-repressor/activator with genetic polymorphisms that have been linked to germ cell tumor formation in humans." (PMID 35244684, 2022). "Some studies have shown that disruption of the ATF7IP-SETDB1 complex in tumor cells can restore the expression of tumor antigens, which provides a rationale for cancer immunotherapy targeting SETDB1 or ATF7IP." (PMID 39583200, 2024). "ATF7IP knockout induces interferon signaling through IRF7 and IRF9 upregulation, enhancing tumor immunogenicity and anti-tumor immunity via increased T cell activity." (PMID 36497341, 2022). "Our phylogenetic inference analysis showed that the genes ATF7IP and MSH3 could participate in a tumor transition ending in aggressive entities or even carcinomas." (PMID 35563252, 2022).
cancer (9 papers, 2013 to 2025). A tumor composed of atypical neoplastic, often pleomorphic cells that invade other tissues. "To examine how H&E images can be classified based on molecular expression, we chose two cancer‐associated proteins: nuclear ATF7IP/MCAF1 and membranous PD‐L1." (PMID 32012497, 2020). "We then classified the H&E‐stained images by expression levels of cancer‐associated nuclear ATF7IP/MCAF1 and membranous PD‐L1 proteins using immunohistochemistry of serial sections." (PMID 32012497, 2020). "Furthermore, inspecting the tissue distribution of the mutations in ATF7IP that are reported in the catalogue of somatic mutations in cancer (COSMIC) database demonstrated a significant bias toward copy number variation (CNV) gains in testis." (PMID 34795250, 2021). "Collectively, these results indicated that the expression of ATF7IP/MCAF1 and PD‐L1 is correlated with tissue characteristics, suggesting that the spatial appearance of the cancer‐associated proteins reflects morphological information of the pathological tissues." (PMID 32012497, 2020). "Because the interaction with Atf7IP is critical for Setdb1-mediated silencing of retrotransposons, disrupting this interaction may be an attractive strategy to reduce immune evasion of cancers." (PMID 40339988, 2025). "Since most of the chromatin regulators described here (LSD1, PRMT7, SETDB1, KDM5B, and ATF7IP) converge functionally, it will be crucial to identify additional cancer-specific factors the targeting of which may be less toxic." (PMID 36497341, 2022). "MCAF1 (also known as hAM or ATF7IP), a transcriptional cofactor that is overexpressed in various cancers, functions in gene activation or repression, depending on interacting partners." (PMID 23935871, 2013).
ATF7IP also shares sentences with these, for which no sentence is quoted: bladder (2 papers); Bladder Cancer (2); B-cell lymphoblastic leukemia (1); colon cancer (1); diabetes (1); esophageal squamous cell carcinoma (1); Huntington disease (1); influenza (1); Intellectual disability (1); leukemia (1); liver cancer (1); lung carcinoma (1); macular holes (1); osteonecrosis (1); otitis media (1); retinal detachment (1); testicular germ cell tumor (1).